HK2 (hexokinase 2)
Diseases named in the same sentence as HK2 in open-access papers (continued):
Sharing a sentence is not in itself a finding about the gene and the disease.
tumor (continued). "To conclude, these data confirmed that HK2 could promote tumor growth in vivo and may have an effect on the ERK signaling pathway." (PMID 37854321, 2023). "Furthermore, coincident observations were achieved by xenograft model, showing that the promoting effects of UBR7 decline on tumor growth and metastasis was impaired by silencing HK2." (PMID 36419136, 2022). "HK2 is overexpressed in cancer and mediates aerobic glycolysis, tumor growth, and metastases." (PMID 35626002, 2022). "Thus, tumor HK2 expression/glycolysis should be further investigated as potential biomarkers or therapeutic targets in the era of cancer immunotherapy." (PMID 36320008, 2022). "Tumor HK2 expression was more closely related to lymphoid cells compared with myeloid cells." (PMID 36320008, 2022). "Under pro-angiogenic stimuli in a tumor context, the endothelial glycolytic rate increases and different glycolytic enzymes (e.g., hexokinase 2 (HK2) and pyruvate kinase (PK)) relocate into migratory cell structures, such as lamellipodia and filopodia, favoring cell migration." (PMID 35681715, 2022). "We detected the mRNA levels of lncRNA CASC7, HK2 and miR-143-3p in tumour tissues." (PMID 35474307, 2022). "Differential effects of 4EBP1-4A on the translation of HK1 and HK2 suggest that 4EBP1 may regulate glucose and insulin metabolism to inhibit tumor growth, and this needs to be explored." (PMID 35626002, 2022). "Moreover, overexpression of HK2 attenuated the effect of chrysin on apoptosis and tumor glycolysis, pointing out that HK2 plays an important role in chrysin-mediated glycolysis suppression." (PMID 35890106, 2022). "In order to investigate the biological role of HK2 on regulating the proliferative activity in vivo, 106 OVCA433-HK2 and SKOV3-HK2 and their control cells were inoculated subcutaneously into female nude mice to identify the role of HK2 in regulating tumor formation in vivo." (PMID 35711830, 2022). "On the contrary, HK2 silencing could inhibit glycolysis and induce oxidative phosphorylation in hepatocellular carcinoma, and synergistically inhibit the growth of mouse tumor cells with sorafenib." (PMID 36042519, 2022). "Similarly, HK2 protein levels were also elevated in tumor cell lines in contrast with the normal cell line." (PMID 35265223, 2022). "Such as, several HK inhibitors, including the catalytic inhibitors 3-Bromopyruvate (3-BrPyr), Lonidamine, and the glucose-analogue, competitive inhibitor 2-Deoxyglucose (2-DG) both target HK2 in many tumor models, detach it from mitochondria and elicit tumor cell death." (PMID 36072431, 2022). "An increase in HK2 expression may contribute to shaping the immunosuppressive/pro-tumorigenic tumor microenvironment by modulating the CD8 + T-cell to Treg ratio." (PMID 36320008, 2022). "In addition, immunohistochemical analysis showed that the expression of SIRT6, HIF-1α, HK2 and Ki-67 in tumor tissues of the PC9/SIRT6 group was higher than that of the PC9/vector group." (PMID 35915188, 2022). "HK2 is necessary for accelerating glucose flow, tumor initiation, and maintenance." (PMID 36216804, 2022). "Moreover, a positive correlation between glycolytic genes (HK2, PFKM, and PKM2) and a high Ki67 index was also observed, which is indicative of their association with cell proliferation and tumor aggressiveness." (PMID 35328104, 2022). "The high expression of HK2 was further identified as an independent risk factor of RCC patients; it also showed a significant positive immune cell infiltration RCC tumor microenvironment including macrophages, B cells, neutrophils, dendritic cells, and CD8+ T cells." (PMID 35265223, 2022). "In some cancers, the binding ability of HK2 to mitochondria significantly increased which reduces the permeability of the mitochondrial outer membrane, thus enhancing the catalytic activity of HK2 and thus glycolysis, ultimately leading to tumor growth and metastasis." (PMID 35265223, 2022).
tumor (continued). "With silenced HK1, HK2 positive tumor cells become more sensitive to HK2 inhibition." (PMID 36358940, 2022). "Some inhibitors of HK2, such as 2-deoxyglucose and 3-bromopyruvate, can inhibit glycolysis of a variety of tumor cells and exhibit anticancer effects, suggesting that HK2 may be an effective anticancer target." (PMID 35265223, 2022). "Moreover, knockdown of HK2 leads to tumor growth inhibition in prostate, glioblastoma, and pancreatic cancers." (PMID 35328104, 2022). "Genetic ablation of HK2 results in tumor growth inhibition in mouse models." (PMID 35626002, 2022). "It has been reported that HK2 plays an important role in tumor biology." (PMID 36335239, 2022). "Also, the upregulation of HK2 can be mediated by the hypomethylation of its promoter, which promotes HK2 expression and tumor progression." (PMID 36319992, 2022). "Most immortalized and malignant cells show increased expression of HK2, which may contribute to an increase in glycolysis and provide energy and metabolites for tumor DNA synthesis." (PMID 35957825, 2022). "Moreover, the alignment between adjacent normal tissues from GTEx and tumour specimens from TCGA database reflected that high expression of HK2 was determined in most malignant cancers." (PMID 35982398, 2022). "The genetic alteration status of HK2 in different tumor samples of the TCGA cohorts was analyzed." (PMID 36335239, 2022). "The function of hexokinase-2 (HK2) in connecting ATP from oxidative phosphorylation to the rate-limiting step of glycolysis may aid tumor cell growth." (PMID 35057031, 2022). "An increase in tumor HK2 expression/glycolysis may contribute to shaping the immunosuppressive/pro-tumorigenic tumor immune microenvironment by modulating/decreasing the ratio of tumor-infiltrating CD8 + T-cells to regulatory T-cells in human cancers." (PMID 36320008, 2022). "Furthermore, mutations in the UBA domain of p62 increased the mitochondrial localization of HK2 and promoted tumor cell survival." (PMID 35328718, 2022). "MiR-143 was discovered to be an important determining factor of tumor glycolysis by targeting HK2." (PMID 36483029, 2022). "HK2 (hexokinase 2) is located in the outer membrane of mitochondria, participates in most glucose metabolism pathways, and is thought to be involved in the supply of tumor cells." (PMID 35600868, 2022). "HK2, a key metabolic enzyme, can promote the Warburg effect and tumor growth." (PMID 35719058, 2022). "Studies have shown that the expression level and activity of HK2 in metastatic NB tumor tissues are higher than those in local NB tumor tissues, suggesting that HK2 plays an important role in the formation of the malignant phenotype of NB and affects the progression of the disease." (PMID 36713522, 2022). "In conclusion, downregulating lncRNA CASC7 could inhibit tumour proliferation by reducing glycolysis through the miR-143-3p/HK2 axis." (PMID 35474307, 2022). "This study showed that BIRC5, SLCO4A1, POPDC3, and HK2 were significantly downregulated in stage MS NB and affected the survival rate of children, indicating that the low expression of these four genes is a factor conducive to tumor regression." (PMID 36713522, 2022). "Thus, we concluded that lncRNA CASC7 affects tumour glycolysis and proliferation by regulating HK2 expression." (PMID 35474307, 2022). "Additionally, the present T-cell subsets within the TME significantly differed according to the level of HK2 tumor expression." (PMID 36320008, 2022). "Also, glioblastoma cells exposed to xanthohumol resulted in inhibition of HK2 expression and impaired tumor glycolysis." (PMID 35890106, 2022). "Subsequently, to further investigate the function of HK2 on regulating cell motility and tumor metastasis in human cervical cancer cells, exogenous HK2 was stably overexpressed by transfection of an HK2 recombinant plasmid in HeLa (HeLa-Vec and HeLa-HK2) and SiHa (SiHa-Vec and SiHa-HK2) cells." (PMID 34758823, 2021).
tumor (continued). "Moreover, microRNA-455 (miR-455) served as a tumor suppressor by directly interacting with HK2 mRNA and inhibiting its expression." (PMID 34174908, 2021). "Additionally, IHC analysis demonstrated that GLUT1 and HK2 protein levels were downregulated in tumor tissues of sh-circC6orf132 group relative to sh-NC group." (PMID 34659329, 2021). "High HK2 expression correlates with the size of the tumor, pathological grade, and prognosis." (PMID 34181336, 2021). "Tumor cells often express high levels of the glycolytic enzymes hexokinase 2 (HK2) and 6-phosphofructo-2-kinase/fructose-2,6-biphosphatase 3 (PFKFB3), or switch isoforms of metabolic enzymes such as PKM (Alves-Filho and Pålsson-McDermott, 2016; Lincet and Icard, 2015)." (PMID 34345916, 2021). "It has been proven that it can suppress tumor growth by inhibiting HK2 so that it may be an antitumor agent." (PMID 34721037, 2021). "The expression of HK2 mRNA in human tumor samples was further analyzed by TIMER database." (PMID 34708035, 2021). "HK2 gene expression data were collected in a total of 365 different types of tumor studies." (PMID 34174908, 2021). "Importantly, Doppler ultrasound analysis of microbubble perfusion revealed that treatment with HK2 inhibitor enhanced LLC tumor blood flow and perfusion in mice as compared with the groups treated with either placebo or doxorubicin alone." (PMID 34650057, 2021). "This study demonstrated that HK2 could activate Akt1 in cervical cancer cells, subsequently enhancing cell motility and tumor metastasis by inducing FN1, MMP2 and MMP9 expression." (PMID 34758823, 2021). "However, evidence about the role of HK2 in regulating cell motility and tumor metastasis during the cervical cancer malignant progression remains limited." (PMID 34758823, 2021). "Doppler ultrasound analysis of microbubble perfusion revealed that depletion of HK2 in TPC enhanced A549 tumor blood flow and perfusion in mice as compared with scramble control group, while overexpression of ROCK2 in HK2-depleted TPC reduced the enhanced tumor blood flow and perfusion observed." (PMID 34650057, 2021). "Inhibition of HK2 expression in tumor cells effectively depressed the development of tumor cells." (PMID 33718248, 2021). "Importantly, co-immunostaining analysis confirmed that LLC tumor pericytes expressed HK2, while the expression of pericyte-p-MLC2 was reduced in LLC/A549 tumors after treated with HK2 inhibitor as compared with placebo." (PMID 34650057, 2021). "Notably, treatment with HK2 inhibitor or doxorubicin alone showed limited/modest effect on tumor growth as compared to placebo treated group." (PMID 34650057, 2021). "Confirming these findings in vivo, we observed that in orthotopic CCA mice a number of critical metabolic genes such as Pfkp, fatty acid synthase (Fasn), Atp6 (p < 0.001) and hexokinase 2 (Hk2) (p < 0.0001) are upregulated in tumor liver and metastatic liver LNs." (PMID 34831316, 2021). "Finally, we performed HE staining, immunofluorescence staining, immunohistochemical staining, and Western blot analysis on nude mouse tumor tissues to detect protein expression changes in HK2, GLUT1, Ki67, PCNA, CDK2, CyclinD1, Bax, and Bcl-2." (PMID 34893086, 2021). "However, the combination of HK2 expression knockdown and TX treatment exhibited significant tumor growth suppression when compared to HK2 expression knockdown or TX treatment alone." (PMID 34174908, 2021). "Staining indicated the upregulation of HK2 in CRC tumour tissues." (PMID 34378321, 2021). "Importantly, the combination of the HK2 inhibitor 3‐bromopyruvate (3‐bp) and oxaliplatin significantly suppresses tumour growth in vivo." (PMID 34378321, 2021). "Moreover, HK2-induced autophagy was proposed to be involved in chemotherapeutic resistance of some tumor models." (PMID 33946854, 2021). "However, evidence regarding the potential role of HK2 in regulating cell motility and tumor metastasis during the cervical cancer malignant progression remains limited." (PMID 34758823, 2021).
tumor (continued). "Furthermore, HK2 is a pivotal factor in cancer metabolism, called the “Warburg effect”; the active tumor increases the expression of HK2 by upregulating the glycolysis metabolism for survival." (PMID 34068051, 2021). "Researchers have demonstrated that increased levels of HK2 in PDAC patients indicates a poor prognosis, especially because HK2 may induce tumor progression by stimulating lactate production in PC cells." (PMID 33669111, 2021). "Additionally, HK2 silencing also synergized with sorafenib, a multi-tyrosine kinase and angiogenesis inhibitor, to inhibit tumor growth." (PMID 34359547, 2021). "Thus, targeting HK2 can be used to sensitize cancer cells to radiotherapy and control tumor cells’ growth and proliferation." (PMID 34181336, 2021). "Although the promoting effect of HK2 on malignant cell growth and tumor metastasis has been reported in many types of cancers, the potential role of HK2 in regulating cell motility and tumor metastasis in cervical cancer cells remains unclear." (PMID 34758823, 2021). "Moreover, we further identified that HK2 expression was associated with clinical stage, LNM and tumor diameter in BC." (PMID 34345220, 2021). "Previous studies have shown that the expression of HK2 in tumor cells is regulated by c-Myc." (PMID 33718248, 2021). "Both RT-PCR and western blot analysis indicated that the conditioned medium of 3-BP or/and DOX pre-treated tumor cells could still up-regulate HK2 and ROCK2 expression in NSCLC/HCC-derived NPC as compared to untreated NPC group." (PMID 34650057, 2021). "This indicated that HK-2 played an important role in tumor glycolysis and malignant process." (PMID 34922556, 2021). "HK2, a regulator of glucose metabolism, is essential for tumor initiation and maintenance." (PMID 34345220, 2021). "Therefore, we supposed that such stimulation of FN1 in HK2-overexpressing cells was probably responsible for the promoting effect of HK2 on cell motility and tumor metastasis in cervical cancer." (PMID 34758823, 2021). "We found that patients with tumour recurrence had higher HK2 expression." (PMID 32279420, 2020). "HK2 silencing acted synergistically with sorafenib to inhibit HCC tumor growth in mice." (PMID 32542016, 2020). "As to its role in GBM, HK2 was also reported to promote GBM tumour growth by aerobic glycolysis." (PMID 32279420, 2020). "Since metformin treatment could diminish the enhanced oxygen consumption, we hypothesized that HK2 silencing combined with metformin could further enhance the rate of tumor cell apoptosis." (PMID 32083006, 2020). "Also in this condition HIF-1 elevates HK2 and Glut1 expression and increases glucose consumption by tumor cells." (PMID 32493394, 2020). "However, the correlation of KLF4 mRNA levels with the mRNA levels of VEGFA, SLC2A3 and HK2 was only moderate to weak in the analyzed tumor samples (R = 0.5044; R = 0.3348; R = 0.4416)." (PMID 32245394, 2020). "Furthermore, HOTAIR promotes the expression of HK2, and HOTAIR and HK2 are overexpressed in both the serum and tumor tissues of PDAC patients." (PMID 33256814, 2020). "It is generally accepted that HK2 has a dual role in tumor cells that HK2 could not only result in cell growth via enhanced glycolysis but also inhibit apoptosis via binding of VDAC-1 to the mitochondrial outer membrane." (PMID 33425771, 2020). "Additionally, increased protein levels of HK2 were observed in BC specimens compared with those observed in adjacent non‐tumour tissues." (PMID 32885590, 2020). "All of these results demonstrated that the HK2 protein could promote tumor development of SiHa and HeLa cells in vivo." (PMID 33324557, 2020). "Moreover, IHC revealed that the xenografted tumor tissues formed by SiHa-HK2 and HeLa-HK2 exhibited much stronger Ki67 (a cell proliferation marker) and HK2 stains than those formed by their control cells (SiHa-GFP and HeLa-GFP)." (PMID 33324557, 2020). "In fact, HK2 acts as a key regulator of the Warburg effect in tumor cells." (PMID 32331347, 2020).